TRAF2 (TNF receptor associated factor 2)
Diseases named in the same sentence as TRAF2 in open-access papers (continued):
Sharing a sentence is not in itself a finding about the gene and the disease.
lung carcinoma (19 papers, 2013 to 2025). "In cancer research, TRAF2 has been implicated in the biological behavior of various cancers, including bladder cancer and lung cancer." (PMID 38419066, 2024). "We document the molecular docking analysis data of Flupenthixol and desmethylastemizole with the apoptotic regulator proteins CFLAR and TRAF2 linked to lung carcinoma for consideration." (PMID 34602774, 2021). "Oncogenic KEAP1 mutations activate TRAF2-NFκB signaling to prevent apoptosis in lung cancer cells." (PMID 40612112, 2025). "In aggregate, we have shown that KEAP1 mutants R320Q and R470C interact with TRAF2 resulting in its stabilization and activation of NFκB in lung cancer cells." (PMID 38184997, 2024). "TRAF2 is a well-known regulator protein of TNFα-NFκB signaling, shown to be enriched in the GSEA analysis of lung cancer patients with KEAP1 mutation in sites R320 and R470." (PMID 38184997, 2024). "The results indicate that R320Q and R470C mutants of KEAP1 increase S11 phosphorylation and stability of TRAF2, leading to activation of NFκB in lung cancer cells." (PMID 38184997, 2024). "Overall, the data shows that in lung cancer cells with KEAP1 R320Q and R470C mutations, increased TRAF2 and NFκB activity is essential for the anti-apoptotic protection." (PMID 38184997, 2024). "In lung cancer, TRAF2 mediated a positive feedback loop between macrophages and cancer cells that drives tumor growth." (PMID 37415241, 2023). "Our previous study showed that TRAF2 is an attractive radio-sensitizing target for glioblastoma and lung cancer." (PMID 37081115, 2023). "TRAF2 mediates apoptosis in breast, cervical, and lung cancer cells by stabilizing the caspase-2 dimer complex and enhancing its activity to fully commit the cell to death, according to prior research." (PMID 35631261, 2022). "USP17 and OTUD3 promote lung cancer stemness through mediating TRAF2/TRAF3 complex and stabilizing GRP78, respectively." (PMID 32549341, 2020). "In this lung cancer model, TRAF1 affects TRAF2-mediated K48-linked ubiquitination and degradation of BRAF, and thereby promotes the survival and proliferation of lung cancer cells." (PMID 30294322, 2018). "Consistent with the frequent amplification of TRAF2 detected in human epithelial cancers, TRAF2 expression is higher in prostate cancer, pancreatic cancer, lung cancer, stomach cancer, colon cancer, glioblastoma than in normal tissues." (PMID 30294322, 2018). "Confocal analysis further confirmed that TRAF2 co‐localized with CD47 in lung cancer cells." (PMID 39665172, 2025). "Our previous study showed that TRAF2 promoted the growth of glioblastoma and lung cancer cells." (PMID 37081115, 2023). "Furthermore, a crucial role of the TRAF2-NFκB axis as an adaptive survival mechanism in response to EGFR oncogene inhibition has been reported for lung cancer and there is also evidence that TRAF2 expression confers resistance against irradiation." (PMID 36011046, 2022). "In our previously published cancer genomics study TRAF2, another member of the TNF receptor associated factors, was highly significantly repressed by more then 80% but IRAK1 was unchanged in c-Raf transgenic lung cancers." (PMID 24265725, 2013). "Mutations in various upstream regulators (TRAF2, TRAF3, cIAP1&2, CD40) lead to increased stability of NIK and subsequent activation of the noncanonical NF-kB pathway, and this mechanism of activation appears to be important for different cancer types including DLBC and lung cancer." (PMID 34970479, 2021). "Overall, the results suggest that TRAF2-NFκB activation in KEAP1 R320Q and R470C overexpressing A549 cells protects lung cancer cells against apoptosis and that XIAP and BIRC family of proteins regulate the process." (PMID 38184997, 2024). "In lung cancer, USP4 was identified as a negative regulator of TNFα-mediated lung cancer cell migration through deubiquitination of TRAF2 and TRAF6." (PMID 38802791, 2024).
lung carcinoma (continued). "TRAF2 forms a complex with TRAF3 that increased TMAs recruitment mediated by USP17, thereby enhancing stemness and inflammation in lung cancer cells." (PMID 37415241, 2023). "The USP17/TRAF2/TRAF3 complex acts to stabilize its client proteins, enhancing inflammatory responses and stemness in lung cancer cells." (PMID 35874839, 2022). "Knockdown of TRAF2 also enhances TRAIL-induced apoptosis in prostate cancer and inhibits the growth but induces radiosensitization of lung cancer and glioblastoma cells." (PMID 30294322, 2018). "Consistently, USP17 expression in lung cancer cells enhanced basal and stimuli-induced inflammatory responses by stabilizing NIK, c-Rel, and IRF5 through disrupting the TRAF2/TRAF3 complex." (PMID 30038267, 2018). "Increased USP17 expression disrupted the TRAF2/TRAF3 complex formation and stabilized its target proteins, leading to elevated inflammation, stemness, and transformation ability in lung cancer cells and increased macrophage recruitment into tumors." (PMID 30038267, 2018).
colon carcinoma (16 papers, 2014 to 2025). "It has been shown that TRAF2‐mediated K48‐linked polyubiquitination of caspase‐8 prevented TRAIL‐triggered apoptosis in colon cancer cells." (PMID 28972304, 2017). "TRAF2 can also act as an oncogene in solid tumors, e.g., in colon cancer by promoting Wnt/β-catenin signaling." (PMID 36011046, 2022). "LDA prevents β-catenin-TRAF2 interaction and inhibits the Wnt/β-catenin pathway and colon cancer development in a xenogeneic colon cancer model." (PMID 36011046, 2022). "There is also initial evidence that TRAF2 favor colon cancer development beyond its role in the Wnt/β-catenin." (PMID 36011046, 2022). "Colon cancer (CC) cell lines show TRAF2 and TRAF3 expressions in 30–60% of the cases, while they are not or weakly expressed in normal colon tissues." (PMID 34257589, 2021). "TRAF2 expression is elevated in prostate, pancreatic, lung, and colon cancer than in normal tissues." (PMID 31130821, 2019). "Moreover, TRAF2 has been described as being a dominant oncogenic driver of colon cancer development supporting the Wnt-β-catenin signaling pathway." (PMID 40229245, 2025). "Similarly, genetic alterations of TRAF2 are also identified in 2.7% (12/439) of human colon cancers (TCGA, PanCancer Atlas)." (PMID 30294322, 2018). "An LDA analog selectively targeted TRAF2 with higher binding affinity than LDA, inhibiting Wnt and TNF signaling and hindering the growth of colon cancer cells in xenograft mice." (PMID 40229245, 2025). "Otherwise, the protein expression levels of TRADD, H2AC6, VDAC3, JMJD7-PLA2G4B, TRAF2, and DAPK1 in colon cancer tissues and normal tissues in the HPA database were shown, which were consistent with the expression levels of these genes in RNA levels." (PMID 36505813, 2022). "In present study, we demonstrated that the expression of IL-32α concomitantly increased the signaling complex of TNFR1 with TRADD, TRAF2, and RIP1 in colon cancer cell, AOM-induced CRC mice, and colon cancer patient tissues." (PMID 25909160, 2015). "Alterations of TRAF2 and TRAF3 in colon cancer (CC) along with their regional difference and microsatellite instability (MSI) are largely unknown." (PMID 34257589, 2021). "A dominant oncogenic driver of colon cancer development is the Wnt/β-catenin signaling pathway culminating in the formation and activation of a nuclear transcriptional complex containing β-catenin, T-cell factor 4 (TCF4) and the TRAF2- and Nck-interacting kinase (TNIK)." (PMID 36011046, 2022). "Colon cancer is possibly not the only tumor entity where the β-catenin-TRAF2 axis gains relevance." (PMID 36011046, 2022).
melanoma (16 papers, 2015 to 2025). A malignant, usually aggressive tumor composed of atypical, neoplastic melanocytes. "This concurs with findings that the TRAF2/PIAS2/ELAVL1/EPHA5 pathway is pivotal in IL-17A-induced melanoma." (PMID 40809015, 2025). "In IFNγ-resistant melanoma cells, TRAF2 and cIAP1 were identified as key factors increasing sensitivity to CD8 + T-cell mediated killing by lowering the TNF cytotoxicity threshold and, therefore, increasing immunotherapy efficacy." (PMID 40229245, 2025). "To further explore the molecular mechanisms driving tumor sensitivity to CD8 T cell-mediated killing, we challenged wild-type (WT) and TRAF2 knockout (KO) melanoma cells with healthy donor CD8 T cells using a matched co-culture system." (PMID 41315176, 2025). "Using this information, we performed a matched co-culture study using a melanoma cell line that is only sensitized to T cell killing upon TRAF2 KO and treatment with Birinipant, a SMAC mimetic targeting cIAP1/2." (PMID 41315176, 2025). "In melanoma cells, findings suggest that TRAF2 sustains the downstream signaling of IL-17, increasing aggressiveness." (PMID 40229245, 2025). "Introducing the protein into human melanoma cells was shown to inhibit TNF, IL-1, TLRs, and TNF receptor-associated factor 2- (TRAF2-) induced NF-κB activation, thereby restoring the SAPK or NF-κB response to TNF activation." (PMID 34194957, 2021). "Missense mutations at R372 (R372C, H or S) of the TRAF-C domain of TRAF2 are detected in eight patients with HNSCC, melanoma, and prostate, uterine, cervical, stomach, and liver cancers (TCGA; COSMIC)." (PMID 30294322, 2018). "Interestingly, the level of TRAF2 mRNA was reduced in FKBP51 knockdown melanoma cells." (PMID 26101251, 2015). "IL-17A stimulation recruits ELAVL1 and PIAS2 via TRAF2, stabilizing EPHA5 mRNA and promoting melanoma cell proliferation and invasion." (PMID 40809015, 2025). "TRAF2 loss was found to be significantly enriched in responders in the overall pan-cancer cohort (p = 1.8 × 10−4), as well as urothelial cancer (p = 8.0 × 10−3), melanoma (p = 3.2 × 10−2), and borderline nonsignificance in the “other tumor types” cohort (p = 7.0 × 10−2) as individual cohorts." (PMID 33508232, 2021). "Indeed, TRAF2 silencing reduces proliferation and increases radiosensitivity in GBM and enhances immunotherapy efficacy in melanoma." (PMID 41226485, 2025). "Induces EPHA5 via TRAF2 to recruit PIAS2 and ELAVL1 to promote melanoma development." (PMID 39906741, 2024). "IL-17 also induces EPHA5 via TRAF2 to recruit PIAS2 and ELAVL1 to promote melanoma development." (PMID 39906741, 2024). "In melanoma cells, extracellular S1P activated NFκB, and this was correlated with expression of actin-binding protein FlnA, an interaction partner of SPHK1 and TRAF2." (PMID 36672428, 2023). "Genetic alterations of TRAF2 are detected in 3–4% of human HNSCC and melanoma." (PMID 30294322, 2018). "However, the loss of TRAF2 does not significantly impair the efficacy of immunotherapy in HNSCC, but it does in urothelial cancer and melanoma." (PMID 36900006, 2023).
multiple myeloma (15 papers, 2013 to 2025). "Among the rare paradoxical effects of TRAF2, TRAF2 inactivating mutations increase alternative NF-κB pathway activation in mantle cell lymphoma, diffuse large B-cell lymphoma and multiple myeloma." (PMID 40229245, 2025). "Gene expression studies performed by Kuehl and colleagues showed that multiple myeloma is associated explicitly with TRAF2 and TRAF3 gene mutations that promote activation of the NFκB system via an alternative pathway." (PMID 39061149, 2024). "For example, inactivating mutations of TRAF2 have been associated with tumor development, e.g., in multiple myeloma and mantle cell lymphoma." (PMID 36011046, 2022). "In approximately 20% of multiple myeloma cases loss-of-function mutations for TRAF2, TRAF3 and cIAP1/2 have been identified in patients, leading to NIK-induced activation of both the canonical and alternative NF-κB pathways to regulate cell growth and survival." (PMID 23301098, 2013). "It has been found that patients with multiple myeloma, hepatocellular carcinoma, and prostate cancer are characterized by increased expression of TRAF2." (PMID 39061149, 2024). "Certain multiple myeloma cell lines have genetic defects in TRAF2/3 and cIAP1/2, which degrade NIK protein." (PMID 37005661, 2023). "Here, we investigated the relationship between interleukin-6-induced proliferation of multiple myeloma cells and Traf2- and Nck-interacting kinase (TNIK) expression in Wnt signaling." (PMID 28467797, 2017). "Our data indicate that increased expression of NFκB regulators have an anti-myeloma effect, and this is supported by the high frequency of inactivating mutations found in these regulators (BIRC3, Traf2/3 and CYLD) in myeloma patients." (PMID 26015393, 2015). "Mutations leading to constitutive activation of the kinase NIK in multiple myeloma have been found in NIK itself, that disrupts its binding with TRAF3, in turn causing dissociation of NIK from the inhibitory complex having TRAF2 and the ubiquitin ligases cIAP1 and cIAP2." (PMID 36899924, 2023). "The analysis of TRAFs or cIAPs mutant multiple myeloma and cIAPs- or TRAFs-deficient MEFs demonstrated that NIK degradation is ensured by the TRAF3-TRAF2-cIAP1 ubiquitin ligase complex, in which TRAF3 serves as NIK-binding component and recruits cIAPs via TRAF2." (PMID 32365919, 2020). "Whereas loss-of-function mutations of TRAF2 or cIAP2 have been described in MCL and DLBCL, inactivating mutations or homozygous deletions of the gene encoding TRAF3 have been reported in HL (15% of cases), DLBCL (15%), and in multiple myeloma (50%)." (PMID 29587428, 2018). "Additionally, the deubiquitinase CYLD, which negatively regulates NF-κB activation by removing K63-linked polyubiquitin chains from IKKγ, TRAF2, and TRAF6, is frequently inactivated by deletion, mutation, or transcriptional silencing in multiple myeloma." (PMID 29587428, 2018). "In hematopoietic cancer cells such as multiple myeloma and adult T-cell leukemia as well as lung cancer cells, either stabilization of the NIK protein through impaired negative regulation by the TRAF3/TRAF2/cIAP complex or aberrant expression of the NIK mRNA have been reported." (PMID 24533079, 2014). "Several studies showed that loss-of-function mutations of TRAF2, TRAF3 or cIAP1/2 protects NIK from proteasomal degradation leading to accumulation of NIK and subsequent constitutive noncanonical NF-κB activation in multiple myeloma cells." (PMID 24533079, 2014).
gastric cancer (12 papers, 2017 to 2025). A primary or metastatic malignant neoplasm involving the stomach. "Although TRAF2 has less evidence in the GBM, several reports support that TRAF2 is associated with migration of gastric cancer cells by regulating TRAF2." (PMID 35052701, 2021). "Lower CHIP or higher TRAF2 was significantly linked to shorter overall survival in gastric cancer patients." (PMID 31130821, 2019). "As TRAF2 was involved in K48‐linked polyubiquitination of caspase‐8, we examined the potential role of TRAF2 in mediating K48‐linked polyubiquitination of caspase‐8 in gastric cancer cells." (PMID 28972304, 2017). "Overexpression of TRAF2 WT increased TRAIL‐induced K48‐linked polyubiquitination of caspase‐8 in gastric cancer cells." (PMID 28972304, 2017). "In gastric cancer, overexpression of TRAF2 has been associated with a poorer prognosis." (PMID 38825674, 2024). "TRAF2-silencing also attenuated in vitro the migration and invasion capacities of gastric cancer cells." (PMID 40229245, 2025). "DR5, CBL-b/c-CBL, and TRAF2 form the complexes in TRAIL-resistant gastric cancer cells that target CBL-b and c-CBL by inhibiting the interaction of TRAF2 with caspase-8 and subsequent caspase-8 multiubiquitination." (PMID 39130630, 2024). "The results showed that DR5-CBL-b/c-CBL-TrAF2 complex inhibited the TRAIL-induced apoptosis of gastric cancer cells by promoting TRAF2-mediated caspase-8 polyubiquitination." (PMID 39130630, 2024). "Although TRAF2 has less evidence in the GBM, there are several reported supporting that TRAF2 associated with migration of gastric cancer cells by regulating TRAF2." (PMID 35052701, 2021). "TRAF2 influenced diverse aspects of cellular behavior of gastric cancer cells, including cell growth, migration, and invasion, which was in contrast to the functions of CHIP." (PMID 31130821, 2019). "Stably transfected CHIP-shRNA and TRAF2-shRNA AGS gastric cancer cell lines were established using Lipofectamine 2000." (PMID 31130821, 2019). "Increased TRAF2 expression is recognized as a prognostic factor in pancreatic cancer, stomach cancer, and glioblastoma." (PMID 30294322, 2018). "This indicated that TRAF2 is the critical factor in regulating TRAIL sensitivity in gastric cancer cells." (PMID 28972304, 2017). "Another important question is why DR5‐Cbl‐b/c‐Cbl‐TRAF2 complex formed in TRAIL‐resistant gastric cancer cells." (PMID 28972304, 2017). "To confirm the role of TRAF2 in polyubiquitination of caspase‐8, we silenced TRAF2 in gastric cancer cells and confirmed that TRAF2 siRNA attenuated TRAIL‐induced K48‐linked polyubiquitination of caspase‐8 in TRAIL‐resistant cells." (PMID 28972304, 2017). "In this study, DR5, casitas B‐lineage lymphoma‐b (Cbl‐b)/c‐Cbl, and TRAF2 formed a complex in TRAIL‐resistant gastric cancer cells, and Cbl‐b and c‐Cbl were the critical adaptors linking DR5 and TRAF2." (PMID 28972304, 2017). "In gastric cancer cell lines, TRAF2 silencing diminished the proliferation, migration and invasion." (PMID 40229245, 2025). "Overexpression of TRAF2 enhances the malignant phenotype of gastric cancer cells." (PMID 36012427, 2022). "TRAF2 expression is independent prognostic factors of gastric cancer." (PMID 31130821, 2019). "Furthermore, the expression of CHIP was downregulated while the expression of TRAF2 was upregulated in gastric cancer tissues." (PMID 31130821, 2019). "The expression of CHIP and TRAF2 was negatively correlated in the gastric cancer tissue." (PMID 31130821, 2019). "Furthermore, the oncoprotein cag PAI of H. pylori activates NF-κB and induces IL-8 secretion through the TRAF2/TRAF6-NIK-IKK pathway in gastric cancer cells." (PMID 30294322, 2018). "miR‐141, by targeting Cbl‐b and c‐Cbl, inhibits TRAF2‐mediated K48‐linked polyubiquitination and degradation of caspase‐8, which leads to the induction of apoptosis and hence increases the sensitivity of TRAIL in gastric cancer cells." (PMID 28972304, 2017).